DSG1 (desmoglein 1)
Description:
A component of desmosome cell-cell junctions which are required for positive regulation of cellular adhesion. Promotes differentiation of keratinocytes via interaction with ERBIN. Reduces activation of RAS/ERK signaling pathways in keratinocytes via promoting ERBIN localization to the cell membrane and its interaction with SHOC2, this competitively reduces the formation of RAS-SHOC2 ERK-activating complexes. Mediates the interaction between the desmosome and COP9 signalosome complex (CSN) protein complex. As a result of this interaction, promotes keratinocyte differentiation via deneddylation of EGFR resulting in a reduction in EGFR protein stabilization and translocation away from the cell membrane. Critical for epidermal integrity and barrier function of the skin (By similarity). Required for esophageal epithelial barrier integrity and correct intercellular spacing in differentiated esophageal epithelium. Required for recovery of epidermal architecture and correct expression of differentiation markers following UVB exposure. May also be required for OCLN involvement in tight junctions (By similarity).
Synonyms: DG1; CDHF4; DSG; EPKHE; EPKHIA; PPKS1; SPPK1
Tractability: Antibody: UniProt places it where antibodies can reach, with high confidence; its Gene Ontology location is reachable by antibodies, with high confidence; UniProt predicts a signal peptide or a membrane-spanning region.
Gene: Protein-coding gene on chromosome 18 (31,318,160 to 31,359,246, forward strand). Ensembl gene ENSG00000134760.
Subcellular location: Cell membrane; Cell junction, desmosome; Cytoplasm; Nucleus
Pathways (Reactome):
Developmental Biology: Formation of the cornified envelope; Keratinization
Signal Transduction: RND2 GTPase cycle; RND3 GTPase cycle
Immune System: Neutrophil degranulation
Programmed Cell Death: Apoptotic cleavage of cell adhesion proteins
Gene Ontology:
Molecular function: gamma-catenin binding; protein binding; calcium ion binding; toxic substance binding
Biological process: cellular response to UV-B; epithelial cell-cell adhesion; positive regulation of epidermal cell differentiation; positive regulation of keratinocyte differentiation; positive regulation of protein localization to plasma membrane; protein stabilization; calcium-dependent cell-cell adhesion; cell-cell adhesion; cell-cell junction assembly; establishment of skin barrier; inflammatory response; cell adhesion; homophilic cell-cell adhesion; maternal process involved in female pregnancy; response to progesterone
Cellular component: cell junction; cell-cell junction; cytoplasm; cytoplasmic side of plasma membrane; desmosome; nucleus; plasma membrane; cornified envelope; cytosol; ficolin-1-rich granule membrane; apical plasma membrane; lateral plasma membrane; membrane
Genetic constraint (gnomAD): Loss-of-function variants: 33 observed, 96.99 expected, observed/expected ratio (o/e) 0.34, 90% interval 0.26 to 0.46. The upper end of that interval is the gene's LOEUF score, 0.46, which puts it in group 2 of 6, group 1 being the genes least tolerant of losing a copy. Missense variants: 1,293 observed, 1,341.7 expected, observed/expected ratio (o/e) 0.96, 90% interval 0.92 to 1.01. Synonymous variants: 471 observed, 460.26 expected, observed/expected ratio (o/e) 1.02, 90% interval 0.95 to 1.1.
Homologues: Orthologues: chimpanzee DSG1 (98% identical), macaque DSG1 (92% identical), rabbit DSG1 (83% identical), dog DSG1 (83% identical), pig DSG1 (81% identical), mouse Dsg1b (79% identical), mouse Dsg1a (79% identical), rat Dsg1 (78% identical), guinea pig DSG1 (70% identical), mouse Dsg1c (69% identical), tropical clawed frog dsg1 (40% identical). Paralogues in human: DSG4 (43% identical), DSG3 (39% identical), DSG2 (34% identical), DSC2 (20% identical), DSC3 (19% identical), DSC1 (19% identical).
Diseases named in the same sentence as DSG1 in open-access papers:
DSG1 is named in the same sentence as 123 diseases in open-access papers, as found by Europe PMC text mining. Sharing a sentence is not in itself a finding about the gene and the disease. The quoted sentences say what the papers report.
pemphigus (146 papers, 2006 to 2026). Pemphigus is a group of rare autoimmune diseases that cause blistering of the skin and mucous membranes (mouth, nose, throat, eyes, and genitals).This conditioncan occur at any age, but often strikes people in middle or older age. "The primary autoantigens in both forms are Dsg1 and Dsg3, which are considered the most important pathogenic targets in pemphigus." (PMID 40642697, 2025). "PF is a superficial variant of pemphigus, characterized by the presence of autoantibodies directed against Dsg1." (PMID 40831828, 2025). "Pemphigus represents a spectrum of potentially life‐threatening autoimmune‐mediated skin blistering conditions caused by antibody production against desmoglein 1 and 3 (anti‐DSG 1 and 3) in keratinocytes." (PMID 39460496, 2024). "Pemphigus is caused by autoantibody production against desmoglein 1 and 3 (anti‐DSG1 and DSG3), which are involved in the cell‐to‐cell adhesion of keratinocytes." (PMID 39460496, 2024). "IgG autoantibodies targeting desmoglein-1 and -3, the pivotal desmosome adhesion molecules, are hallmark features characterizing the spectrum of pemphigus autoimmunity." (PMID 39203983, 2024). "Lesion formation of pemphigus is the result of pathogenic autoantibodies that target desmoglein-3 (Dsg3) and desmoglein-1 (Dsg1), located on the surface of epidermal keratinocytes." (PMID 39062594, 2024). "Pemphigus is caused by autoantibodies that target desmoglein 1 and desmoglein 3, impacting desmosome function." (PMID 38213911, 2023). "Pemphigus is a life-threatening bullous autoimmune disease in which autoantibodies against Dsg1, Dsg3, Dsc3 as well as other antigens cause flaccid blistering in the epidermis and in mucous membranes of the oral cavity and elsewhere." (PMID 36624106, 2023). "In these conditions, acantholysis is due to direct disruption of desmosomes, either through the production of autoantibodies against Dsg1 in pemphigus or mutations in Dsg1 or desmoplakin in SAM syndrome." (PMID 37471166, 2023). "The main three pemphigus variants are: Muco-cutaneous pemphigus vulgaris (PV) which shows antibodies against Dsg1 and Dsg3 and affects the epidermis and the mucosa." (PMID 35711465, 2022). "In a prospective study on pemphigus relapses in rituximab‐treated patients, lower Dsg1 levels were associated with longer time to relapse." (PMID 34288016, 2022). "Pemphigus is a severe autoimmune blistering skin disease disrupting desmosomes and is caused by autoantibodies predominantly against Dsg1 and Dsg3, which finally compromises the integrity of epidermal and mucosal tissue." (PMID 35711465, 2022). "Whereas autoantibodies against Dsg1 are also present in patients with pemphigus foliaceus (PF), another major clinical variant of pemphigus that displays a phenotype of blistering in the superficial epidermis." (PMID 33796116, 2021). "The most common clinical variant of pemphigus, pemphigus vulgaris (PV), is generally associated with Dsg3 for the mucosal-dominant phenotype, and both Dsg1 and Dsg3 for the mucocutaneous/cutaneous phenotype." (PMID 33796116, 2021). "Pathogenic pemphigus autoantibodies targeting Dsg1 and Dsg3 are mostly directed against EC1 and 2, while antibodies directed for example against EC5 are reported to be non-pathogenic." (PMID 34434944, 2021). "Pemphigus is an autoimmune blistering disease of the skin and mucous membranes caused by autoantibodies against desmoglein 1 (Dsg1) and desmoglein 3 (Dsg3)." (PMID 32509225, 2020). "Pemphigus is driven by pathogenic antibodies to both desmoglein (Dsg) 1 and 3 (PV, mucocutaneous type), or Dsg3 (PV, mucosal dominant-type), or Dsg1 (PF)." (PMID 32642305, 2020). "Pemphigus foliaceus (PF) is an autoimmune bullous disease caused by autoantibodies against desmoglein-1 (Dsg-1)." (PMID 33077743, 2020). "The clinical phenotype of pemphigus (i.e., the site of blister formation) is determined by the underlying antibody profile and the normal tissue distribution of Dsg1 and Dsg3." (PMID 31552014, 2019).
pemphigus (continued). "Their results demonstrated a higher sensitivity and specificity for IIFm (Dsg1: 100%, 100%; Dsg3: 100%, 78%, respectively) compared with IIFc that support the use of IIFm to improve the diagnostic accuracy of pemphigus." (PMID 29872685, 2018). "The simpler model proposes that pemphigus pathogenic autoAb inhibit, either sterically or allosterically, the interaction of DSG1 and DSG3 from desmosomes of adjacent keratinocytes (trans-interaction), inducing loss of cell adhesion." (PMID 28928733, 2017). "Pemphigus is an autoimmune disease in which IgG auto-antibodies (auto-ab) against the desmosomal cadherins desmoglein (Dsg) 3 and Dsg1 cause loss of epidermal keratinocyte adhesion." (PMID 26872212, 2016). "Pemphigus is an antibody (ab)-mediated autoimmune disease in which auto-ab mainly directed against the desmosomal cadherin Desmoglein (Dsg) 3 and Dsg1 cause loss of keratinocyte adhesion in the human skin." (PMID 26872212, 2016). "Pemphigus is a group of autoimmune skin blistering diseases caused by loss of cell-cell adhesion due to autoantibodies binding to Dsg1 and Dsg3 resulting in the internalization of desmosomes." (PMID 25785582, 2015). "The pemphigus vulgaris antigen is a 130 kDa protein, Dsg3, which belongs to the cadherin superfamily of calcium-dependent adhesion proteins while Dsg1 is the target of autoantibodies in pemphigus foliaceus, a superficial variant of pemphigus." (PMID 23781320, 2013). "Pemphigus is a family of potentially fatal autoimmune blistering skin diseases caused by autoantibodies directed against desmosomal cadherins desmoglein 1 (Dsg1) and desmoglein 3 (Dsg3)." (PMID 23226536, 2012). "The recent availability of cDNA clones for pemphigus antigens has allowed the production of recombinant DSG1 and DSG3 molecules and the development of an enzyme-linked immunosorbent assay (ELISA) approach in order to determine levels of antibodies to them." (PMID 20049340, 2009). "Finally, another study on biomarkers predictive of relapse in rituximab‐treated pemphigus patients showed that the relapse was associated with positivity for either anti‐Dsg1 or anti‐Dsg3 antibodies in serial ELISA tests after rituximab treatment." (PMID 34288016, 2022). "Finally, pemphigus foliaceus (PF) with antibodies against Dsg1 causes acantholysis in the epidermis only." (PMID 35711465, 2022). "Pathogenic autoantibodies in pemphigus are mostly directed against Dsg1 and Dsg3." (PMID 34434944, 2021). "The interpretation of the desmoglein compensation theory, as it relates to the clinical findings in pemphigus, can be summarized as follows: patients with antibodies against only desmoglein 3 should have mucosal-dominant PV because desmoglein 1 compensates for the loss of desmoglein 3 in skin." (PMID 34684117, 2021). "We hypothesized that the immunodominant P. papatasi salivary protein PpSP32 binds to desmogleins 1 and 3 (Dsg1 and Dsg3), triggering loss of tolerance to these pemphigus target autoantigens." (PMID 33108348, 2020). "In addition, activation of ERK1/2 is also involved in the pathogenesis of pemphigus, an autoimmune blistering skin disease caused by autoantibodies against DSG1 and DSG3." (PMID 32556797, 2020). "Furthermore, we investigated whether inhibition of ADAMs also play a role in human keratinocyte models for pemphigus, a blistering disease in which autoantibodies mainly against Dsg1 and Dsg3 lead to a loss of cell adhesion." (PMID 35844545, 2022). "In pemphigus, autoantibodies against the desmosomal cadherins desmoglein (DSG) DSG1 and DSG3 cause intraepidermal blistering." (PMID 41657310, 2026). "To further clarify the correlation between Dsg1 and Dsg3 and clinical symptoms, we divided patients with pemphigus into PV (Dsg1-Dsg3+, Dsg1+Dsg3+) and PF (Dsg1+Dsg3-)." (PMID 40661962, 2025). "In pemphigus, autoantibodies target Desmoglein 1 (Dsg1) and 3 (Dsg3), desmosomal cadherins that link adjacent keratinocytes." (PMID 40661962, 2025).
pemphigus (continued). "Salivary antigens from Simulium pruinosum (“black fly”) induce a cross-reaction leading to the production of autoantibodies against DSG1 in Brazilian pemphigus, where the disease occurs in members of the same family living near water." (PMID 40098967, 2025). "Drug-induced pemphigus involves Dsg 1 and 3, and IgA predominantly Dsg-1 (subcorneal pustulosis) or Dsg 1 and 3 in the deeper forms." (PMID 40098967, 2025). "In pemphigus patients, anti-Dsg1 antibody level was higher in the severe group than in the mild group." (PMID 40661962, 2025). "The clinical phenotypes of pemphigus depend on the autoantibody profile and the target antigens, which are mainly Dsg1 and/or 3 in PV and Dsg1 in PF." (PMID 40098967, 2025). "Dsg1, Dsg3, Dsc1-3, mitochondrial proteins and subtypes of the acetylcholine receptor are the major antigens of pemphigus." (PMID 40098967, 2025). "The levels of anti-Dsg1 and anti-Dsg3 were significantly higher in pemphigus patients, whereas the levels of anti-BP180 and anti-BP230 were significantly elevated in BP patients compared to both disease control patients and healthy volunteers." (PMID 40661962, 2025). "Autoantibodies in pemphigus primarily target Dsg1 and Dsg3, with additional antibodies against desmosomal and non-desmosomal proteins contributing to disease complexity." (PMID 40372624, 2025). "Autoantibodies in the sera from pemphigus patients predominantly react with the extracellular (EC) domains of Dsg1, particularly its N-terminal adhesive region." (PMID 40372624, 2025). "The results demonstrated that anti-Dsg1 and anti-Dsg3, exhibited superior performance in differentiating between healthy individuals and pemphigus, with AUC values of 0.96 (95%CI: 0.93~1) for anti-Dsg1 and 0.91 (95%CI:0.86~0.96) for anti-Dsg3." (PMID 40661962, 2025). "In the case of coexistence of SLE and PV, ANA are detected; desmoglein 3 is present in the case of pemphigus vulgaris limited to the mucous membranes or DSG3 and DSG1 in the case of pemphigus of the mucous membranes and skin." (PMID 39860415, 2025). "Among them, 87% of patients with pemphigus were positive for either anti-Dsg1 and anti-Dsg3 antibodies, and 79.25% of patients with BP were positive for either anti-BP180 and anti-BP230 antibodies." (PMID 40661962, 2025). "This pattern is typical of pemphigus disorders and reflects the deposition of Dsg1-specific autoantibodies bound to desmosomes on the keratinocyte surface." (PMID 40831828, 2025). "Desmoglein 3 autoantibodies are expressed in the mucosal dominant phenotype of pemphigus (pemphigus vulgaris) and desmoglein 1 autoantibodies are present in cutaneous pemphigus." (PMID 38256427, 2024). "Risk factors for pemphigus relapse include patients with high PDAI at onset, high BMI, high affected BSA, non‐mucosal pemphigus subtypes, PV, and high DSG1 and DSG3 populations after treatment." (PMID 39460496, 2024). "The pathological role of anti-desmoglein-1 IgG antibodies is well-established, as evidenced by the development of pemphigus-like symptoms when patients’ sera or purified IgG are injected into neonatal mice." (PMID 39203983, 2024). "The hallmark feature of pemphigus is the immune system’s predominant attack on desmoglein (DSG) proteins, primarily DSG-3, DSG-1, or both DSG-3/DSG-1." (PMID 38399557, 2024). "Pemphigus is an autoimmune disease that affects the skin and mucous membranes, induced by the deposition of pemphigus IgG, which mainly targets desmogleins 1 and 3 (Dsg1 and 3)." (PMID 39201550, 2024). "Autoantibodies targeting desmoglein 1 and desmoglein 3 play a significant role in the occurrence and development of pemphigus." (PMID 39654895, 2024). "There are different clinical forms of pemphigus which histologically correlate with the molecular and structural expression of Dsg1 or Dsg3 in the epidermis and mucous membranes." (PMID 39201550, 2024).
pemphigus (continued). "While pemphigus antigens Dsg1 and Dsg3 are functionally glycosylation independent, the glycosylation profile of PV IgG is drastically altered." (PMID 39450179, 2024). "Expression of Dsg1 and Dsg3 is basically restricted to stratified squamous epithelia, where blisters are formed in pemphigus, while Dsg2 is expressed in all desmosome-possessing tissues, including simple epithelia and myocardium." (PMID 39593117, 2024). "The conventionally recognized antigenic targets in the pemphigus group of diseases are desmoglein 3 (Dsg3) and desmoglein 1 (Dsg1), members of the calcium dependent cadherin superfamily of transmembrane cell adhesion molecules." (PMID 39759530, 2024). "Pemphigus develops due to the production of anti‐DSG1 and DSG3 antibodies by errant autoreactive B‐cells." (PMID 39460496, 2024). "Several signaling pathways have been implicated in the downstream effects of DSG1 and DSG3 depletion in pemphigus." (PMID 37237515, 2023). "ELISAs are typically performed using commercial kits to assess the most commonly occurring autoantibodies seen in AIBD, i.e., DSG1 & DSG3 antibodies in pemphigus, BP180 & BP230 antibodies in pemphigoid diseases and collagen VII antibodies in EBA." (PMID 38074463, 2023). "Pemphigus is a kind of bullous autoimmune disorder in which the autoimmune system targets its own desmosomes (mostly Dsg-1 and Dsg-3) of the mucocutaneous membranes by autoantibodies, resulting in loss of connectivity between keratinocytes." (PMID 38125430, 2023). "The pemphigus antigens Dsg1 and Dsg3 were downregulated and the keratin cytoskeleton was severely compromised." (PMID 36624106, 2023). "Recent progress in molecular biology has revealed that IgG autoantibodies of classical pemphigus react with Dsg1 or Dsg3." (PMID 36578135, 2023). "Drugs can also induce pemphigus through the production of immunoglobulin (Ig) G autoAb against Dsg-1 and 3, provoking an immunologic acantholysis." (PMID 38213911, 2023). "The detection of IgG antibodies against Dsg1 and 3 is extremely useful to confirm the diagnosis of autoimmune bullous diseases of the pemphigus group." (PMID 36263026, 2022). "For example, pemphigus is characterized by circulating anti-desmoglein 1/3 (Dsg1/3) autoantibodies that target the desmosomal adhesion molecules anchoring epidermal keratinocytes." (PMID 35924234, 2022). "We focused on co-localization of the pemphigus autoantigens Dsg1 and Dsg3 with plaque proteins Pg and Dp." (PMID 35711465, 2022). "The hallmark of pemphigus is the presence of autoantibodies against the desmosomal cadherins desmoglein 3 (DSG3, in PV) and desmoglein 1 (DSG1, in PF and patients with mucocutaneous PV) on the cell surface of neighboring epidermal keratinocytes." (PMID 35632621, 2022). "In this study, we aim to enlighten the understanding of pemphigus pathogenesis by investigating the fate of Dsg1 in response to PF-IgG regarding its dynamics and intramembrane localization and the involvement of the cytosolic Ca2+ signaling." (PMID 35634274, 2022). "Anti-desmoglein 1 and 3 autoantibodies justify acantholysis in pemphigus; however, the pathogenesis of anti-desmoglein 2 is hypothetical." (PMID 35058080, 2022). "Pemphigus is a life-threatening autoimmune bullous disease, and the patients have autoantibodies targeting the adhesion proteins (Dsg1 or 3) among keratinocytes, leading to acantholysis of skin and mucous membrane." (PMID 35783635, 2022). "Since the exact pathomechanism in pemphigus remains elusive, we attempted to further investigate the role of Dsg1, as antibodies directed against Dsg1 appear crucial for skin blistering in pemphigus." (PMID 35634274, 2022). "We have established that skin infiltrating lymphocytes in pemphigus lesions can produce Dsg1/3 antibodies in vitro which makes them valuable study subjects." (PMID 35449056, 2022).